IL6 (interleukin 6)
Diseases named in the same sentence as IL6 in open-access papers (continued):
Sharing a sentence is not in itself a finding about the gene and the disease.
COVID-19 (continued). "IL-6 elevation widely exists in COVID-19 infected patients, that may increase the platelet counts." (PMID 40160330, 2025). "Additionally, these botanical drugs suppressed the production of proinflammatory cytokines, such as IL-6 and TNF-α, both of which have been implicated in the cytokine storm that is associated with ARDS, which is a major cause of death in patients with COVID-19." (PMID 40385477, 2025). "With the growing application of immune-targeted therapies, agents such as the IL-6 inhibitor (tocilizumab), which has shown potential benefit in managing delirium among critically ill COVID-19 patients, may warrant future investigation in AID populations for both prevention and treatment." (PMID 40740958, 2025). "In our study, patients with SARS-CoV-2 infection had lower levels of inflammatory markers such as CRP, procalcitonin, and IL-6 compared to non-COVID-19 patients, suggesting that reduced inflammatory burden may contribute to the higher cholesterol and LPC levels observed in this group." (PMID 41007672, 2025). "Due to the observational and cross-sectional nature of our study, we are unable to determine whether the elevated IL-6 levels observed in COVID-19/Self-RPD+ patients result from additive inflammatory effects or from a synergistic interaction between the two conditions." (PMID 40647649, 2025). "COVID-19 patients aged ≥55 yr had a lower BMI (29.4 vs 32.7), a higher rate of non-survivors (62% vs 28%), a significantly increased rate of cardiovascular (P=0.0156) and respiratory (P=0.0297) disease, and significantly higher concentrations of IL-6 (P=0.0314) than COVID-19 patients aged ≤55 yr." (PMID 40529720, 2025). "IL6 upregulation in the brain therefore is consistent with the cytokine ‘storm’ observed in COVID-19 and consequently plays a critical role in driving the thrombotic pathology observed in COVID-19 patients’ brain, and can be potentially be targeted for ameliorating this risk in patients." (PMID 41141600, 2025). "Additionally, as one of the inflammatory factors, interleukin-6 (IL-6) was increased in severely affected coronavirus disease-2019 (COVID-19) patients, and could significantly increase the risk of arrhythmic events via affecting cardiac ion channel functions." (PMID 41327470, 2025). "Cytokines of particular interest include interleukin-6 (IL-6), tumor necrosis factor-alpha (TNF-α), interleukin-8 (IL-8), and interleukin-10 (IL-10), each having been linked to mortality in conditions such as acute cardiac events, renal failure, sepsis, ARDS, and notably COVID-19." (PMID 40843708, 2025). "Moreover, COVID-19 patients with co-infections exhibited even higher levels of IL-6, CRP, and PCT, suggesting that bacterial co-infections may amplify the inflammatory response and worsen patient outcomes." (PMID 40046064, 2025). "In addition, IL-6 is highly related to overt inflammatory reactions in patients with COVID-19." (PMID 40843373, 2025). "Moreover, while inflammatory (e.g., CRP, IL-6) and coagulation (e.g., D-dimer) markers may mediate the relationship between chronic diseases and COVID-19 mortality, our study prioritized variables routinely documented in clinical practice." (PMID 40463970, 2025). "Furthermore, ivermectin modulates host immunity by downregulating nuclear factor kappa B (NF-κB) signaling and reducing levels of key pro-inflammatory cytokines such as IL-6 and TNF-α, which are implicated in the cytokine storm observed in severe COVID-19 cases." (PMID 40426524, 2025). "The systemic inflammatory response observed in acute COVID-19, characterized by elevated levels of cytokines, such as IL-2, IL-10, IL-6, IL-8, C-Reactive Protein (CRP), and Tumor Necrosis Factor (TNF)-alpha, triggers acute phase reactions and, if sustained, may lead to end-organ damage." (PMID 40029921, 2025).
COVID-19 (continued). "For instance, in a retrospective study done in China involving 1,149 COVID-19 patients found that SUA levels over 6.7 mg/dL were associated with higher levels of the inflammatory markers such as tumor necrosis factor-α (TNF-a), Interleukin-6 (IL-6), and ferritin." (PMID 40333671, 2025). "Sepsis patients with a history of severe COVID-19 exhibited elevated IL-6, IL-1β, and IL-17 levels, prolonged APTT, and increased 28-day mortality, indicating that past severe COVID-19 infection may contribute to systemic inflammation and coagulation disturbances, further worsening prognosis." (PMID 41305706, 2025). "Additionally, mebendazole may exert immunomodulatory effects by downregulating pro-inflammatory cytokines such as IL-6 and TNF-α, which are implicated in the cytokine storm associated with severe COVID-19." (PMID 40426524, 2025). "High levels of IL-6 and IL-10, adjusted for age, sex, the presence of comorbidities, and the neutrophil-to-lymphocyte ratio (NLR), showed an elevated risk (OR IL-6 = 4.02; OR IL-10 = 9.36) of presenting pneumonia and COVID-19 compared to pneumonia without COVID-19 in patients." (PMID 40508859, 2025). "Likewise, it has been reported that patients with T2DM and COVID-19 had a higher count of white blood cells, neutrophils, and proinflammatory cytokines (such as IL-6 and TNF-α), suggesting an increased inflammatory response compared to patients without diabetes." (PMID 40406515, 2025). "Thus, evaluating the tissue expression of IL-6, IL-1β, and IL-18 in a sensory nerve could provide information about neuroinflammation related to neuropathic pain in post-COVID-19 conditions." (PMID 41516235, 2025). "Although some studies demonstrated an increase in creatine metabolite levels, similar to inflammatory markers such as CRP and IL-6, in patients with COVID-19, our study indicated that fluctuating creatine levels in patients in the ICU could be predictive of different prognostic outcomes." (PMID 40608744, 2025). "However, the same findings on incidence of severe COVID-19 were used successfully as evidence for IL-6 inhibition in severe COVID-19, so we can have some confidence that our genetic findings might translate therapeutically." (PMID 40819633, 2025). "Thus, it is hypothesized that an optimal vitamin D level may modulate the inflammatory response by reducing the activity of interleukin-6 (IL-6) and interferon gamma (IFNγ), two predictors of unfavorable clinical outcome in severe COVID-19." (PMID 40427060, 2025). "In addition, another report showed that increased glycolysis and interleukin-6 signaling in cytotoxic T cells were significantly higher in patients with delayed severe COVID-19 compared to patients with usual severe COVID-19, particularly in the middle and late stages of infection (Kim IS." (PMID 40880642, 2025). "The identified IL-6/glucose-NK cell axis may explain the exacerbated severity of COVID-19 in patients with diabetes, where pre-existing metabolic stress (chronic hyperglycemia) and acute viral-induced inflammation create a 'double-hit' scenario on antiviral immunity." (PMID 40471558, 2025). "Therefore, this research may contribute to further our understanding of the role of IL-6, ferritin, C-reactive protein, hepcidin, and zinc in COVID-19 patients residing at different altitudes." (PMID 39062181, 2024). "Furthermore, deferoxamine lowers the amounts of IL-6, a major inflammatory cytokine generated during COVID-19, suggesting that deferoxamine may be used as a medication to treat COVID-19-induced PD." (PMID 38503730, 2024). "Also, all patients had already been exposed to the antigen (vaccinated or previous COVID-19), so they could have mounted an immune response different from the primary response, which could also have masked the correlation of IL-6 and TGF-β1 with SIgA." (PMID 38541764, 2024). "Therefore, it may be possible to treat inflammation induced by COVID-19 and alleviate symptoms in AR patients by specifically inhibiting IL-6." (PMID 39057037, 2024).
COVID-19 (continued). "Moreover, IL-6 has been recently described as a COVID-19 severity predictor." (PMID 39582872, 2024). "Furthermore, individuals with a moderate to severe risk of OSA, in the absence of concurrent COVID-19, exhibited elevated levels of serum IL-6 in contrast to those with a mild risk of OSA." (PMID 38476500, 2024). "Additionally, periodontal disease may worsen COVID-19 symptoms by contributing to higher IL-6 production." (PMID 38800223, 2024). "Thus, we hypothesize that IL-6 upregulation in COVID-19, as well as IL-3 and IL-11 upregulation, is likely involved in the stimulation of megakaryocytes and possibly also resident megakaryocytes in the lung." (PMID 38786077, 2024). "Furthermore, COVID-19 can induce the release of cytokines, such as interleukin-1β, interleukin-6, and tumor necrosis factor-α, which may lower serotonin levels by altering its biosynthesis, release, and reuptake." (PMID 38792343, 2024). "However, several other studies suggested that immunosuppressants may be beneficial to patients infected with COVID-19 by mitigating cytokine storms, such as anti-interleukin (IL)-6 antibodies and anti-tumor necrosis factor (TNF) therapy." (PMID 39538233, 2024). "Thus, these interleukin levels cannot be compared to those described by other authors for direct dosing from COVID-19 patients serum (IL-6: 19.55 pg/mL mean; IL-10: 3.66 pg/mL mean; TNF-α: 1.11 pg/mL mean) or vaccinated participants serum (IL-6: 25.94 pg/mL mean; IL-10: 11.08 pg/mL mean)." (PMID 38728294, 2024). "Indeed, it has been shown that higher expression of IL-6 is seen in severe cases of COVID-19." (PMID 38612524, 2024). "Th2 inflammation suppresses the production of proinflammatory cytokines such as IL-1β, TNF-α, and IL-6, which are important for defense against viral infections, but also play a role in the late phase of hyperinflammation, which is the typical phase of COVID-19 leading to severe disease." (PMID 38921725, 2024). "Although not previously associated with COVID-19, sphinganine-1-phosphate showed anti-inflammatory properties by attenuating neutrophil infiltration in the kidneys and liver and reducing plasma levels of IL-6 and TNF-α." (PMID 39595969, 2024). "In order to investigate whether such a phenomenon is also present in mild convalescent COVID-19 patients, we quantified IL-6, sIL-6R and sgp130 via ELISA in serum samples from 49 healthy unexposed individuals (HD), 68 mild COVID-19 convalescents (MC) and 25 acute severe COVID-19 patients (ICU)." (PMID 39835136, 2024). "Recent studies have reported that COVID-19 patients are mostly in a high systemic inflammatory condition with excessive cytokine releases which is characterized by high levels of interleukin-6 (IL-6), IL-8, and tumor necrosis factor-α (TNF-α) that contribute to deadly complications." (PMID 39395941, 2024). "Inhibition of dipeptidyl peptidase 4 (DPP4) could suppress T-cell proliferation and IL-6 and IL-10 secretion, which regulate the immune response to COVID-19 and reduce inflammation, which has been shown to provide cardiovascular and cognitive benefits to the population." (PMID 39777148, 2024). "The in-hospital treatment protocols for COVID-19 from the United States National Institutes of Health (2023) and the World Health Organization (2023) are not unanimous in their recommendations and include using anticoagulants, corticosteroids, antivirals, IL-6 inhibitors or JAK inhibitors." (PMID 38370482, 2024). "Severe COVID-19 is characterized by an inflammatory profile that involves initial immune evasion by downregulation of Type I Interferon pathways along with significant upregulation of IL-6, IL-8 and TNF-α in the lungs that coincides with increased NF-κB activity." (PMID 37938797, 2024).
COVID-19 (continued). "The administration of corticosteroids may be considered to distinguish between cytokine storms and anaphylaxis post vaccination, and the monitoring of IL-6 levels may provide a more accurate diagnosis and appropriate treatment of adverse effects from the COVID-19 mRNA-LNP vaccine." (PMID 39452475, 2024). "Importantly, other research groups are currently focusing on investigating whether selectively blocking IL-6 trans-signaling could reduce symptoms and severity in COVID-19 while preserving the host defense activity of classical IL-6." (PMID 39518964, 2024). "Therefore, the relationship between the use of IL-6 antagonists and the occurrence of thromboembolic events in patients with COVID-19 remains unclear." (PMID 38321099, 2024). "Moreover, COVID-19 in the acute phase and PACS are associated with high levels of interleukin-6." (PMID 39200115, 2024). "Thus, IL-6 signaling markers may be valuable not only as indicators of severity, but also in developing novel treatment options in COVID-19 patients." (PMID 39452786, 2024). "However, we could detect a significantly decreased expression of IL6 in the blood of COVID-19-infected females, an observation that was also made by others." (PMID 38298642, 2024). "The data suggest that IL-6 may significantly drive eGC damage in COVID-19 and bacterial sepsis." (PMID 38598083, 2024). "In addition, for COVID-19 patients with elevated IL-6 levels, timely administration of tocilizumab may improve cytokine release syndrome and reduce the risk of disseminated intravascular coagulation (DIC)." (PMID 38493138, 2024). "Interestingly, ‘insulin resistance’ in COVID-19 could lead to both ‘IL-6 signalling and inflammation’ and ‘NET formation’." (PMID 38778394, 2024). "This includes the pivotal cytokine IL-6, which plays a role in fever induction and acute phase protein synthesis through the IL-6 receptor expressed by neutrophils; and interestingly that it has also emerged as a pivotal marker in assessing the severity of COVID-19 in humans." (PMID 40303184, 2024). "Furthermore, in COVID-19–related ARDS, the systemic release of proinflammatory cytokines such as interleukin, interleukin-6, and tumor necrosis factor-α, caused both by the virus infection and ventilator-induced lung injury, can activate proapoptotic pathway and fibrosis in the kidneys." (PMID 38899195, 2024). "The importance of inflammatory cytokines such as TNF-α and IL-6 is further demonstrated by the fact that blockade of individual cytokines resulted in a partial rescue of cardiomyocyte viability, confirming serological cytokine-driven cardiotoxicity in COVID-19." (PMID 38041432, 2024). "The study revealed that both uncontrolled hypertension and long COVID resulted in elevated IL-6 and IL-17 concentrations, peaking in patients with both conditions and decreasing over time after infection, possibly reflecting Th17-related systemic inflammation during the acute phase of COVID-19." (PMID 38424126, 2024). "Studies on histological tissues from COVID-19 patients, have described how the virus can induce an inflammatory reaction both at systemic and local hepatic level, through the activation of inflammatory cytokines interleukin 6 (IL-6) and interferon gamma-induced protein (IL-6 e IP-10)." (PMID 38713731, 2024). "The peculiar inflammatory signature of COVID-19 may be addressed in future research and extend beyond IL-6, as it is possible that its unique molecular features (i.e., lipid metabolism changes and ferroptosis) may guide future treatments and prevent long-term sequelae." (PMID 38256451, 2024). "First we compared the soluble proteome from aIFNpos COVID-19 patients to healthy individuals and observed a significant inflammatory response in aIFNpos patients with drastically elevated levels of proteins such as interleukin 6 (IL-6), IFN-γ, CXCL10, and CCL7." (PMID 38421006, 2024).
COVID-19 (continued). "Similarly, a binary logistic regression model was performed to evaluate IL-6 association in COVID-19 patients with no co-morbidities and CVD patients with RAASI consumption." (PMID 39518552, 2024). "The blend significantly reduced pro-inflammatory cytokines, such as IL-6, while increasing anti-inflammatory IL-10, suggesting that it helps modulate cytokine levels and counteract the hyperactivation caused by SARS-CoV-2, potentially reducing COVID-19 progression and sequelae." (PMID 39599909, 2024). "In acute COVID-19, a significant increase in serum and CSF levels of IL-6 and other cytokines could be demonstrated, which was often associated with BCB dysfunction, partly remaining positive at high levels for weeks and, in the few patients with long-term data tested, even months." (PMID 37999770, 2024). "Additionally, the contrasting performance of IL-6 antagonists, which have shown limited effectiveness in bacterial infections but more success in COVID-19 clinical trials, further illustrates how the efficacy of treatments can vary according to the type of infection." (PMID 39056754, 2024). "Therefore, we speculated that FFYH may be more effective for COVID-19 patients with abnormally elevated IL-6 levels." (PMID 39351097, 2024). "The mechanism by which COVID-19 may cause CAV is not fully understood, but it is thought to be related to the release of pro-inflammatory cytokines such as interleukin 6 and endothelial injury via angiotensin-converting enzyme receptors on the endothelial surface." (PMID 39156367, 2024). "Furthermore, the five cytokines and chemokines with up-regulated expression during the progression of COVID-19 were interleukin 6 (IL-6), interleukin 10 (IL-10), interferon gamma-induced protein 10 (IP-10), TNF-related apoptosis-inducing ligand (TRAIL), and stem cell growth factor beta (SCGF-β)." (PMID 38710800, 2024). "Upregulation of astrocyte gene expression in glial fibrillary acidic protein (GFAP), thrombospondin 2 (Thbs2), leukemia inhibitory factor (Lif), and interleukin 6 (IL-6) by physical activity deserve further studies to explore whether it helps in immune responses, such as those against COVID-19." (PMID 39409085, 2024). "Recently, a secondary analysis of a randomized clinical trial of immunomodulatory therapy in COVID-19 provided evidence that decreases in IL-6 mediated benefit from treatment and that baseline biomarker levels alone could not similarly predict treatment response." (PMID 38441708, 2024). "Recent evidence from COVID-19 patients indicates a significant increase in IL-6 levels in 96% of those investigated, suggesting that proinflammatory cytokines and acute inflammation may play a crucial role in the disturbed lipid metabolism observed in COVID-19 patients." (PMID 37511334, 2023). "Notably, anti-IL-6 aAbs were predominantly elevated in asymptomatic COVID-19 females." (PMID 37243300, 2023). "First, we studied the profile of different soluble pro-inflammatory cytokines (GM-CSF, TNF-α, IFN-γ, IL-1β, IL-2, IL-6, IL-7, IL-10, IL-17A, IL-21) and chemokines mediating monocyte and neutrophil recruitment (IL8, CCL3), whose exacerbated production is associated with severe COVID-19." (PMID 36675231, 2023). "Finally, the CsA-engineered powder showed an anti-inflammatory effect in terms of IL-6 reduction that could also be useful in containing the COVID-19 cytokine storm in the lungs." (PMID 36986883, 2023). "A 3-month cardiopulmonary rehabilitation program in the post-acute COVID-19 phase improves recovery of endothelium-dependent vasodilation, arterial stiffness, and arterial reflected waves, especially in patients with high levels of IL-6 before the initiation of cardiac rehabilitation." (PMID 36983234, 2023).